BLK (BLK proto-oncogene, Src family tyrosine kinase)
Diseases named in the same sentence as BLK in open-access papers (continued):
Sharing a sentence is not in itself a finding about the gene and the disease.
respiratory failure (1 paper, 2017). The significant impairment of gas exchange within the lungs resulting in hypoxia, hypercarbia, or both, to the extent that organ tissue perfusion is severely compromised. "Given the relationship between POU2AF1, TCL1A, and BLK expression and the development of BOS, we investigated the expression of these three genes in public data sets from blood of patients with other causes of respiratory failure." (PMID 29375549, 2017).
Sepsis (1 paper, 2025). Sepsis is defined as life-threatening organ dysfunction caused by a dysregulated host response to infection. "In this study, BLK exhibited differential expression in six independent sepsis datasets and causal association in four distinct sepsis outcomes (FDRIVW < 0.05)." (PMID 40761792, 2025). "For example, elevated expression of the kinase BLK was strongly associated with a reduction in 28-day mortality risk in sepsis (βIVW = -0.295, FDR = 2.98×10-12)." (PMID 40761792, 2025). "Notably, upregulation of ADCK1, IGF1R, and MAP3K1 at the transcriptional level was found to predict higher sepsis risk, while increased expression of BLK and KCNJ15 correlated with lower risk." (PMID 40761792, 2025). "BLK, a kinase involved in B cell subset development and B cell receptor (BCR) activation, was differentially expressed in B cells in the context of sepsis." (PMID 40761792, 2025).
tumor (16 papers, 2012 to 2025). "Notably, the tumor growth rate was impaired in BLK-deficient group (group 2) in comparison to wild-type group (group 1)." (PMID 37871014, 2023). "Together, these findings suggest BLK inhibition alone will be an ineffective DSRCT therapeutic but combination of BLK inhibition with other therapies targeting bulk tumor cells is worthy of further examination." (PMID 39139449, 2024). "This suggests BLK targeting therapy would be best used in combination with another therapy (e.g., chemotherapy) targeting bulk tumor cells." (PMID 38177125, 2024). "In relevance to cancer, BLK displays opposing roles; it is considered to be a proto-oncogene that increases tumor cell proliferation." (PMID 36199691, 2022). "Both PRV111 and BLK patches were administered to the tumor 5 min after PE application and kept for 1 h under anesthesia." (PMID 35977936, 2022). "Preclinical studies demonstrate constitutive BLK expression increases tumor development and malignant transformation in lymphoma." (PMID 33233470, 2020). "Moreover, BLK deficiency impairs the secretion of downstream antiviral cytokines and promotes Senecavirus A (SVA) proliferation, thereby supporting SVA-induced oncolysis in an in vivo xenograft tumor model." (PMID 37871014, 2023). "While lymphoid aggregates alone did not distinguish between responsive and non-responsive tumours, the integrated analysis revealed higher expression of genes like CD37, MS4A1, BLK, CD79A/B, and TNFRSF13C in responsive tumours’ lymphoid aggregates." (PMID 40141092, 2025). "BLK inhibition will target the CSC population, while chemotherapy eliminates bulk tumor cells, creating a two-pronged therapeutic strategy that accounts for DSRCT heterogeneity and can hopefully improve patient survival." (PMID 38177125, 2024). "Among the tyrosine kinases, the SRC family kinases BLK and LCK as well as the SRC family-related kinase FRK were significantly downregulated in the pAKT-positive T3 xenograft tumor." (PMID 35454789, 2022). "Tumor samples with a positive HPV status expressed significantly higher levels of all of the B cell-related genes analyzed, namely, BLK, CD19, CR2, HLA-DOB, MS4A1 and TNFRSF17." (PMID 31623665, 2019). "In this review we will describe new insights on the role of FoxO, PP2A, p27, BLK, PTEN and other tumor suppressors in CML pathogenesis." (PMID 27184141, 2016). "BLK contributes to immune cell pathways (such as B-cell proliferation and differentiation), indicating that the high expression of the BLK gene in the TN_IM_NSTAS group may regulate the TIME, and it has more immune cell enrichment and anti-tumor effects." (PMID 40786043, 2025). "Moreover, BLK-/- tumor tissues infected with SVA for 3 days showed much higher viral titers and genomic copies than those of infected wild-type tumor tissues." (PMID 37871014, 2023). "Surprisingly, we found a downregulation rather than an upregulation of several Src kinase and Src kinase-related family members—i.e., B-lymphoid tyrosine kinase (BLK), lymphocyte-specific protein tyrosine kinase (LCK) and Fyn-related kinase (FRK)—in the AKT/mTOR-inhibitor-resistant tumor cells." (PMID 35454789, 2022). "Our identification of BLK as a differentially active tyrosine kinase in PDAC cells compared to wild-type pancreatic cells presents new insight into the role that the pancreatic and duodenal homeobox 1 (PDX1) transcription factor plays in tumor progression." (PMID 33213062, 2020). "Intriguingly, studies in a Blk knockout mouse demonstrated that B cell development and the humoral immune response are not substantially impacted by BLK depletion, suggesting BLK-specific inhibitors may have few on-target off-tumor effects." (PMID 39139449, 2024).
cancer (7 papers, 2018 to 2025). A tumor composed of atypical neoplastic, often pleomorphic cells that invade other tissues. "The genes BLK, CDC247, CSK, IRF5, STAT1, STAT4, and TNIP1 are associated with AIDs, and CDC37, DDX6, HSPA6, MAPT, PPIB, STAT1, and STAT4 are associated with cancers." (PMID 40429780, 2025). "The genes BLK, FAM167A, STAT1, STAT4, TNPO3, and TNIP1 are associated with AIDs, and CDC37, DDX6, MAPT, STAT1, STAT4, and UBE3A are associated with cancers." (PMID 40429780, 2025). "BLK is a particularly interesting cancer target because its inhibition or knockdown is likely to have few side effects." (PMID 38177125, 2024). "It appears that the exact role of BLK in cancer development depends on different situations such as the type of cancer." (PMID 36199691, 2022). "Of all of the other family members (FYN, YES, BLK, YRK, FGR, HCK, LCK, and LYN) cSrc is the most often associated with cancer progression." (PMID 33841333, 2021).
infection (2 papers, 2014 to 2023). The state of being infected such as from the introduction of a foreign agent such as serum, vaccine, antigenic substance or organism. "The cytokines induced by SVA infection, including IFN-γ and IFN-λ1, were severely impaired in BLK-/- tumors compared with that of wild-type tumors." (PMID 37871014, 2023).
blood cancer (1 paper, 2018).
genetic diseases (1 paper, 2024). "Some of these such as the LRBA N815S, BLK R456C, and DOCK8 R1154C are only significant because of their observed occurrences in the context of other genetic diseases." (PMID 39415980, 2024).
BLK also shares sentences with these, for which no sentence is quoted: systemic sclerosis (6 papers); immune disease (3); common variable immunodeficiency (2); hyperglycaemia (2); pancreatic cancer (2); polymyositis (2); sarcoma (2); type 1 diabetes (2); vasculitis (2); acute lymphoblastic leukemia (1); alcohol dependence (1); alveolar rhabdomyosarcoma (1); alveolar soft part sarcoma (1); asthma (1); atrial fibrillation (1); Barrett's oesophagus (1); brain infarction (1); cold urticaria (1); cutaneous T-cell lymphoma (1); epilepsy (1); Ewing sarcoma (1); gonococcal infection (1); gout (1); hematologic diseases (1); Hypercholesterolemia (1); Hypertension (1); idiopathic inflammatory myopathies (1); Immunodeficiency (1); Insulin resistance (1); interstitial lung disease (1).
A further 15 diseases each share a sentence with BLK in 1 paper.